CXCR3 (C-X-C motif chemokine receptor 3)
Diseases named in the same sentence as CXCR3 in open-access papers (continued):
Sharing a sentence is not in itself a finding about the gene and the disease.
cancer (continued). "As in other cancers, the CXCR3 paracrine pathway has been phenotypically demonstrated to have an overall anti-tumoral effect in GBM." (PMID 38104126, 2023). "Most IL-4-induced innate CD8 T cells express CXCR3; such cells enhance immunity against bacterial infection and cancer." (PMID 38037190, 2023). "For validation, we examined the expression of CCL17, CXCL14, and CXCR3 in cancer and adjacent tissues of six patients with SLC7A11 overexpression by ELISA." (PMID 35517862, 2022). "This review focuses on CXCR3 and highlights the role of CXCR3 and its ligands in cancer progression." (PMID 36479091, 2022). "CXCL10, CXCL9, CXCL11/CXCR3 is an important axis for immune activation, which is necessary for developing novel cancer therapy." (PMID 36685901, 2022). "We found the influx of NK and Th1 cells to the BM within cancer lesions to be dependent on the chemokine receptor CXCR3, which is expressed on NK cells and T cells, and on its ligand CXCL9, which is induced by IFN-γ." (PMID 35503658, 2022). "CXCR3 activation promotes cancer migration and growth in vitro and in vivo, and both responses can be inhibited and eliminated by a CXCR3 antagonist (AMG487)." (PMID 36479091, 2022). "This suggests that singularly targeting the CXCR3 axis is insufficient for treatment of all cancers." (PMID 35205725, 2022). "ANK2-MT LUAD was characterized by high expression of chemokines (CXCL9, CXCL10, CXCL11, and CXCR3) involved in the recruitment of anti-cancer immune cells." (PMID 36539782, 2022). "For example, CXCL9, CXLC10, and CXCL11/CXCR3 has two main functions: it activates the immune response through the paracrine pathway and promotes the proliferation and metastasis of cancer cells through the autocrine pathway." (PMID 35992864, 2022). "CXCR3 signaling has been reported involving in various human diseases, including chronic inflammation, immune dysfunction, cancer, metastasis, and pruritus." (PMID 35095512, 2021). "As a result, the overexpression of CXCR3 and IFN-γ-inducible chemokines in cancer tissues has been shown to be associated with cancer progression and poor prognosis." (PMID 34501934, 2021). "CXCL10, which is a ligand of CXCR3, is mainly secreted by monocytes, endothelial cells, fibroblasts, and cancer cells." (PMID 34504204, 2021). "Interferon (IFN)-γ-inducible chemokines in the CXCR3/ligand axis are involved in cell-mediated immunity and play a significant role in the progression of cancer." (PMID 34501934, 2021). "Especially, activation of CXCR3 has also been reported to attenuate morphine analgesia in cancer pain." (PMID 34025351, 2021). "CCL5 is another chemokine that we identified as positively associated with the immune response when bound to different receptors (SDC4, SDC1, and CXCR3 for 16, 15, and 13 cancer types, respectively)." (PMID 34430923, 2021). "While it is possible that the cancer cells are responsible for most of the expression which then attracts immune cells, it seems more likely that the CXCR3 expression derives mostly from the immune cells themselves." (PMID 34440489, 2021). "The multi-faceted role of CXCR3 expression in cancer biology warrants further investigation, especially in the context of diverse solid tumor-types and adoptive TCR and CAR T cell therapy." (PMID 34867942, 2021). "To understand the role of CXCR3 in cancer, we used bioinformatic techniques to analyze differential CXCR3 expression, at both the isoform and gene levels, as well as CXCR3 splicing regulation." (PMID 34440489, 2021). "CXCR3 is expressed on activated TILs found in various cancer types, and it is thought to play an important role in T cell migration to inflamed tissues." (PMID 33796916, 2021). "CXCR3 also highlights the importance of alternative splicing in cancer given the apparently opposing roles played by CXCR3-A and CXCR3-B." (PMID 34440489, 2021). "Like in BRCA, some TCGA cohorts and analyses at the gene level did reveal divergent CXCR3 patterns among cancers." (PMID 34440489, 2021).
cancer (continued). "It is worth mentioning that CXCR3, CCR7, and IL10 have been reported to be the underlying mechanisms in cancer metastasis-induced BCP in human." (PMID 34025351, 2021). "CXCL10 is a member of the CXC chemokine family that mediates the recruitment of CXCR3+ CD4+ Type-1 helper (Th1), CD8+ effector and NK cells to inflammatory sites, and has been implicated in the progression of several cancer types." (PMID 34200333, 2021). "The difference between them lies in CXCR3 expression, a chemokine receptor that reportedly contributes to the metastasis of breast and other cancers." (PMID 34831064, 2021). "Our failure to find evidence for altered CXCR3 splicing between tumors and healthy controls seems initially surprising given previous reports of differential expression in cancers." (PMID 34440489, 2021). "In some cancers, there was increased CXCR3 expression in the tumors, while in others there was decreased CXCR3 expression." (PMID 34440489, 2021). "Intriguingly, GSEA revealed that CXCR3+ cancer cells had increased inflammatory- and JNK signaling and showed characteristics of basal cells and stem cells of the mammary gland, in line with the increase of CXCR3+ cells in sphere cultures." (PMID 32198421, 2020). "We show that the ability to promote initiation of tumors and metastases is enriched in CXCR3+ cancer cells compared with CXCR3– cells." (PMID 32198421, 2020). "CXCR3 and its ligands CXCL9 and CXCL10 have been implicated in CTL infiltration into several types of cancer and are positively correlated with a better prognosis." (PMID 32439888, 2020). "Particularly, previous studies have shown that CXCR3/CXCL10 signaling promotes metastasis in several cancer types." (PMID 33195424, 2020). "CXCR3 has been identified as a crucial receptor for NK chemotaxis in response to cancer-secreted ligands, CXCL9, CXCL10, and CXCL11." (PMID 32546200, 2020). "GO term analysis of CXCR3+ cancer cells indicated enrichment of genes involved in inflammatory signaling and chemokine production." (PMID 32198421, 2020). "CXCL10 and its receptor CXCR3 are increasingly being recognized as pro-tumorigenic in several types of cancers." (PMID 32245422, 2020). "The CXCL9, -10, -11/CXCR3 axis is involved in inflammatory responses, leukocyte trafficking, adaptive resistance, hematopoiesis, cancer cell transfer and angiogenesis." (PMID 33585219, 2020). "We show that fibroblast-derived CXCL9/10 promote lung colonization by directly stimulating growth of CXCR3+ cancer cells." (PMID 32198421, 2020). "Although the prognostic effects were different in different solid tumors, these studies all demonstrated the important role of CXCR3 in cancer development." (PMID 33585188, 2020). "In the context of cancer, CXCR3 was found upregulated in many primary and metastatic tumors such as breast, prostate, colon, colorectal, melanoma and ovarian cancer, and associated with poor prognosis." (PMID 31831069, 2019). "The demonstration of the impact of the CXCR3 axis in cancer points to its potential interest as a therapeutic target." (PMID 31216755, 2019). "We observed a high correlation between CD8+ T cell fractions and the expression of CXCL9 chemokine and chemokine receptor CXCR3 and, for some cancer types, with CXCL10 expression." (PMID 31126321, 2019). "Similar to CXCL10, CXCL9 is one of the most extensively studied CXCR3 chemokines in cancer and also plays a dual role in the TME." (PMID 31216755, 2019). "A large number of studies indicated that CXCR3 performs different roles in the tumorigenesis and progression of various cancers." (PMID 31240220, 2019). "The expression level of chemokine receptor (CXCR3) was also significantly altered by co-cultivation with cancer cells." (PMID 31324057, 2019). "It showed that overexpression of CXCR3 stimulated the proliferation and migration of cancer cells in vitro and in vivo, which are related to the progression of malignancies." (PMID 31781593, 2019).
cancer (continued). "The CXCL9/CXCR3 axis regulates immune cell migration, differentiation, and activation and is therefore an important target for cancer therapy." (PMID 31126321, 2019). "Although CXCL10 is only a partial agonist of CXCR3, its impact on many human pathologies including cancer has been extensively studied." (PMID 31216755, 2019). "The IFN-γ/CXCL9, CXCL-10, CXCL-11/CXCR3 axis can be a double-edged sword in cancer, promoting an anti-tumor effect but also increasing the capability of cancer cell proliferation, angiogenesis and metastasis." (PMID 30631766, 2018). "Our results showed an increased level of CXCR3 ligands in nMPTC tissues with thyroiditis, observation that strongly supports the notion that inflammation plays a key role in neoplastic transformation and cancer development through the CXCR3/ligand axis." (PMID 29416784, 2018). "Further, CXCR3 has been considered as a potential therapeutic target for many inflammatory diseases and a few cancer models." (PMID 29707158, 2018). "Cutaneous T cell lymphoma is an unusual situation where CXCR3 expression on malignant T cells helps recruit and establish this cancer within the skin." (PMID 30320116, 2018). "CXCR3 expression on tumor cells promotes cancer metastasis, while its expression on T cells regulates their antitumor reactivity." (PMID 29868034, 2018). "We further refine this work, demonstrating that CXCR3 expression by circulating monocytes is required for efficient engraftment of metastatic-like cancer in the lung." (PMID 28358049, 2017). "CD4+ cell expression of the Th1 marker CXCR3 was increased in cancer septic mice, while expression of the Th2 marker CCR4 was not different between previously healthy septic mice and cancer septic mice." (PMID 27018973, 2016). "The CXCL10 protein and its receptor (CXCR3) have been proposed as therapeutic targets in cancer and in immune-mediated diseases." (PMID 26222498, 2015). "CXCL10 facilitates trafficking of CXCR3-expressing cancer cells to bone, and promotes osteolytic bone metastasis, implying host involvement." (PMID 26485767, 2015). "Globally, both CXCR3 mRNA and protein were elevated in localized and metastatic human cancer biopsies compared to normal." (PMID 22236567, 2012). "Since cancer cell motility is tightly related to cancer invasion, we next examined DU-145 and PC-3 invasiveness in a CXCR3-chemokine environment." (PMID 22236567, 2012). "Finally, the promising therapeutic potential of targeting specific chemokine signaling axes, such as CCL2/CCR2 and CXCL10/CXCR3, was discussed as a strategy to improve the efficacy of cancer immunotherapy." (PMID 41635851, 2026). "Moreover, CXCR3 has three variants, A and B, which exhibit differences in their expression profiles in the TME and have different functions in cancer progression." (PMID 39940842, 2025). "Furthermore, the mechanism of oHSV induces TLS formation and remodels the TME was explored, including the association of CXCL10, and CXCR3 with the cancer patient's prognosis, as well as the impact of blocking CXCL10/CXCR3 pathway on TLS formation." (PMID 39219056, 2025). "Type-II interferon (IFN-γ) inflammatory signaling induces PD-L1 expression on cancer cells, conducive for tumor immune evasion, and at the same time upregulates chemokines such as CXCL9/CXCL10 that recruit CXCR3+ effector T cells as a cytotoxic response to cancer." (PMID 41440526, 2025). "Furthermore, IFN-γ regulates the expression and secretion of CXCL9, CXCL10, and CXCL11, along with their cognate receptor CXCR3 in various immune cells such as T cells, NK cells, monocytes, DCs, and cancer cells." (PMID 40040705, 2025). "Notably, CXCL10 and CXCR3 were favourable prognostic factors for cancer patients, and closely related with immune cells infiltration." (PMID 39219056, 2025). "While it is apparent that the CXCR3/CXCL9 axis is important in cancer, it may depend on the target cell if the interaction has a progressive or inhibitory effect on the cancer cell." (PMID 40362215, 2025).
cancer (continued). "MOC2-7 cells are HNSCC cancer cells derived from a CXCR3 null mouse on a C57BL/6 background." (PMID 39302290, 2024). "However, CXCR3 is also expressed in immunosuppressive regulatory T cells (Tregs) that are particularly enriched in several human cancers, including ovarian and liver carcinomas." (PMID 39596815, 2024). "Interestingly, recent studies using scRNA-seq in CD8+ T cells isolated from patients with cancer have described cells expressing CXCR3 together with GZMK and EOMES as a predysfunctional cell population." (PMID 39485042, 2024). "In addition, three human CXCR3 splice variants—CXCR3A, CXCR3B, and CXCR3-alt—have been identified; these variants function differently in various cancer cell types, and CXCL9, CXCL10, and CXCL11 are ligands for CXCR3." (PMID 38745115, 2024). "In addition, binding of CXCL11 with CXCR3 on CD8+ T cells enhanced the killing activity to cancer cells." (PMID 39543650, 2024). "CXCR3, a chemokine receptor, serves dual autocrine–paracrine functions in cancer." (PMID 38104126, 2023). "CXCL10 promotes CXCR3 expressing cancer cells transported to bone." (PMID 36750966, 2023). "Notably, the known downstream pathways of CXCR3 in cancer significantly impact major protein kinases, such as AKT and PKA." (PMID 38104126, 2023). "Besides recruitment, the potential functions of CXCR3 include T cell priming and positioning, both of which have been proven in other cancers." (PMID 38104126, 2023). "Indeed, cancer cells with higher CXCL10 expression more effectively stimulated migration of CXCR3+ Tregs in a transwell experiment, and the CXCR3 inhibitor AMG487 reduced the number of Tregs recruited to tumors in a mouse model." (PMID 38188682, 2023). "In human specimens, we demonstrated that patients suffering from preoperative cancer-associated pain had higher expression of the receptors CCR7 and CXCR3, respectively, than patients without cancer-associated pain." (PMID 37834436, 2023). "A possible scenario is that PD-L1 and CXCR3 function as immune-suppressive agents in cancer." (PMID 36726488, 2023). "However, our study supports that Cxcr3 is critical for immunotherapy durability through maintaining peripheral GzmB + Klrg1 + effector T cells deemed critical for mitigating cancer cell dissemination." (PMID 36472588, 2023). "In addition, increased CXCL11 expression in cancer-associated fibroblasts (CAFs) promotes the proliferation and migration of EOC cells via CXCR3." (PMID 35269786, 2022). "In addition, CXCR3 chemokine action has been demonstrated to be vital for successful immune checkpoint inhibition in preclinical cancer models, due to both T-cell recruitment and activation." (PMID 35314795, 2022). "On the one hand, CXCL10 secreted by TA-MSCs bind to its cognate receptors CXCR3 presented in cancer cells, and simultaneously, CXCL16 derived from cancer cell bind to CXCR6 on TA-MSCs surface, eventually potentiating the recruitment of TA-MSCs into tumor areas." (PMID 36324128, 2022). "Immunohistochemistry showed that three core proteins associated with the CXCR3 pathway, CXCR3, CXCL9, CXCL10, and were more highly expressed in cancer tissues from the immunotherapy-responder group than in tissues from the immunotherapy non-responder group (n = 1 per group)." (PMID 35562800, 2022). "However, because of the differential expression of CXCR3 in different cancer diseases, its special function in the immune system makes it a potential target for immunotherapy." (PMID 36479091, 2022). "Our results revealed an increased presence of CD8+ CCR6+ CCR5− CXCR3+, which can be correlated with the acquisition of an effector phenotype and further antitumor responses contributing to the immune system‘s action against cancer cells." (PMID 36551555, 2022).
cancer (continued). "Given that CXCR3 alternative splicing is among the clearest single alternative splicing events with effects on cancer, it is perhaps surprising that the mechanism of CXCR3 alternative splicing, A3SS, remains poorly studied, with most genome-wide analyses of splicing focusing on exon skipping." (PMID 34440489, 2021). "The CXCL1 (C-X-C motif chemokine ligand 1) and CXCL10, ligands for chemokine receptor 2 (CXCR2) and chemokine receptor 3 (CXCR3), respectively, are the only members of CXC chemokines family identified as IRDS genes and have been implicated in cancer progression and metastasis." (PMID 33922087, 2021). "CXCL10 is a ligand of the CXC chemokine receptor-3 (CXCR3) and is predominantly expressed by T helper cells (Th cells), cytotoxic T lymphocytes (CTLs), dendritic cells, macrophages, natural killer cells (NKs), as well as some epithelial and cancer cells." (PMID 34422627, 2021). "CXCR3 plays animportant role in angiogenesis, inflammation and cancer." (PMID 33901269, 2021). "However, the expression level of CXCR3 in clinical cancer samples is associated with metastatic potential and patients prognosis, and the affinity of CXCL11 for CXCR3 is the highest of the three selective ligands." (PMID 33777950, 2021). "This relationship may imply that IFN-γ-inducible chemokines show greater affinity for CXCR3 on cancer cells over Th1 immune cells." (PMID 34501934, 2021). "However, investigations have shown that the CXCL9-10-11/CXCR3 axis is able to contribute to the proliferation and metastasis of cancer cells." (PMID 34335758, 2021). "CXCL10 and CXCL11 increase the number of CXCR3-expressing cancer stem cells in BRCA cell lines." (PMID 34067089, 2021). "IP‐10 is a pleiotropic molecule capable of exerting potent biological functions, including promoting the chemotactic activity of CXCR3‐positive cells, inducing apoptosis, and regulating cell growth and proliferation as well as angiogenesis in infectious and inflammatory diseases and cancer." (PMID 34288108, 2021). "CXCR3 expressed on cancer cells has unique action mechanisms." (PMID 34501934, 2021). "These latter act in an autocrine and paracrine manner to stimulate the secretion of the chemokine C-X-C motif chemokine ligand 10 (CXCL10) by cancer cells and thus favor the recruitment of activated T cells expressing its receptor, C-X-C motif chemokine receptor 3 (CXCR3)." (PMID 33281620, 2020). "It should also be noted that CXCR3 is expressed on Tregs and may be involved in directing their recruitment in cancer and transplantation." (PMID 32547545, 2020). "We therefore reasoned that CXCR3+ cancer cells may secrete higher levels of IL-1α/β, in turn leading to elevated production of CXCL9/10 in fibroblasts." (PMID 32198421, 2020). "Additionally, the antagonism of CXCR3 can inhibit other pathological processes in which CXCR3 is involved, such as cancer metastasis." (PMID 32992956, 2020). "The role of Cxcr3 and Cxcr4 signaling axes and their interaction with Ackr3b in cancer progression have not been explored using the zebrafish model in the context of cancer, but it could contribute to clarify the discrepant observations made so far." (PMID 32161595, 2020). "Indeed, isolated CXCR3+ cancer cells expressed higher levels of IL1A/B compared with CXCR3− counterparts, and CM from CXCR3+ MDA-LM2 cells contained higher levels of secreted IL-1α/β." (PMID 32198421, 2020). "In addition to the increased ability of CXCR3+ cancer cells to induce Cxcl9/10 expression in lung fibroblasts, this subpopulation of cancer cells is also likely to benefit from this crosstalk." (PMID 32198421, 2020). "CXCR3 signaling in cancer also presents a therapeutic target." (PMID 32161595, 2020). "To analyze whether CXCR3 in cancer cells is specifically required for metastatic colonization, we transduced 4T1 cells with shRNA against CXCR3 and injected the cells intravenously into BALB/c mice." (PMID 32198421, 2020).